FRAT1 (FRAT regulator of Wnt signaling pathway 1)
Description:
Positively regulates the Wnt signaling pathway by stabilizing beta-catenin through the association with GSK-3. May play a role in tumor progression and collaborate with PIM1 and MYC in lymphomagenesis.
Tractability: Small molecule: a structure with a bound ligand is known. PROTAC: ubiquitination databases record sites on it.
Gene: Protein-coding gene on chromosome 10 (97,319,271 to 97,321,915, forward strand). Ensembl gene ENSG00000165879.
Subcellular location: Cytoplasm
Subcellular location (Human Protein Atlas): Cytosol; Vesicles
Pathways (Reactome):
Signal Transduction: Beta-catenin phosphorylation cascade; Disassembly of the destruction complex and recruitment of AXIN to the membrane
Gene Ontology:
Molecular function: molecular function inhibitor activity; protein binding
Biological process: canonical Wnt signaling pathway; positive regulation of canonical Wnt signaling pathway; regulation of protein export from nucleus
Cellular component: cytoplasm; nucleus; cytosol
Genetic constraint (gnomAD): Loss-of-function variants: 9 observed, 8.03 expected, observed/expected ratio (o/e) 1.12, 90% interval 0.67 to 1.8. That is too few expected variants to judge how well the gene tolerates losing a copy. Missense variants: 354 observed, 284.03 expected, observed/expected ratio (o/e) 1.25, 90% interval 1.14 to 1.36. Synonymous variants: 191 observed, 140.34 expected, observed/expected ratio (o/e) 1.36, 90% interval 1.21 to 1.53.
Homologues: Orthologues: chimpanzee FRAT1 (99% identical), macaque FRAT1 (97% identical), pig FRAT1 (85% identical), mouse Frat1 (76% identical), rat Frat1 (76% identical), rat Peg12 (71% identical), mouse Peg12 (69% identical), dog FRAT1 (68% identical), rabbit FRAT1 (61% identical). Paralogues in human: FRAT2 (67% identical).
Diseases named in the same sentence as FRAT1 in open-access papers:
FRAT1 is named in the same sentence as 27 diseases in open-access papers, as found by Europe PMC text mining. Sharing a sentence is not in itself a finding about the gene and the disease. The quoted sentences say what the papers report.
glioma (7 papers, 2013 to 2024). A benign or malignant brain and spinal cord tumor that arises from glial cells (astrocytes, oligodendrocytes, ependymal cells). "Our previous study confirmed that high FRAT1 expression occurs in human glioma tissue and human glioma cell lines, and its expression is significantly associated with glioma malignancy." (PMID 32201513, 2020). "The detailed mechanism underlying the overexpression of FRAT1 in glioma and its exact role in the Wnt/β-catenin pathway remain to be further investigated." (PMID 25922553, 2015). "FRAT1 may promote the development of gliomas and is associated with various malignancies." (PMID 38672212, 2024). "When the study patients were classified according to the WHO grade, CER1 and FSTL1 showed significantly higher expression, while FRAT1 showed significantly lower expression in patients with grade III glioma than in patients with grade II glioma." (PMID 38672212, 2024). "The expression of four genes (CER1, FRAT1, FSTL1, and RPSA) involved in the Wnt/β-catenin pathway was significantly associated with mortality and disease progression in patients with glioma, especially in those with grade III glioma." (PMID 38672212, 2024). "In contrast, the higher expression of FRAT1 and RPSA in gliomas is associated with better survival and delayed tumor recurrence." (PMID 38672212, 2024). "Existing studies have reported the oncogenic role of FRAT1 in several cancers, such as leukemia, cervical cancer, glioma, and meningioma." (PMID 34319909, 2021). "Our results are the first demonstration that the FRAT1 has the ability to activate the Wnt pathway in glioma stem cells to promote stemness and tumor progression." (PMID 32201513, 2020). "Given the high expression and protumorigenic role of FRAT1 in glioma, we investigated its function and molecular mechanism in GSCs biology." (PMID 32201513, 2020). "Our previous work has showed that compared with the normal human brain cells, FRAT1 was highly expressed in three high grade glioma-derived cell lines U251, U87 and SHG44." (PMID 32201513, 2020). "Further investigation is necessary to define how FRAT1 regulates GSCs through Wnt/β-catenin signaling pathway and then change the characters of glioma." (PMID 32201513, 2020). "Our study confirms that FRAT1 provides vital functions in GSCs, which provides new insights into the role of FRAT1 in tumor progression and reinforces the relevance of FRAT1 and GSCs as viable therapeutic targets for glioma." (PMID 32201513, 2020). "Real-time PCR, Western blot, and Immunohistochemistry were processed to detect the mRNA and protein expressions of FRAT1, β-catenin in the glioma tissue of xenograft mice to study their correlations." (PMID 32201513, 2020). "Western blot analysis also showed reduced protein levels of FRAT1 and β-catenin in glioma tissues of mice-FRAT1-KD." (PMID 32201513, 2020). "FRAT1 expression is positively correlated with proliferation of glioma and seriously affects patient prognosis." (PMID 32201513, 2020). "Through small animal MRI to examine glioma growth in brains of xenograft nude mice, we confirmed that downregulated FRAT1 expression inhibited the GSCs proliferation in vivo." (PMID 32201513, 2020). "Then, an intracranial glioma nude mouse model was built to measure the effect of low FRAT1 expression on GSCs proliferation and tumorigenesity in vivo." (PMID 32201513, 2020). "We have demonstrated that FRAT1 mRNA and protein are highly expressed in glioma tissues and glioma cell lines, with expression being elevated with increasing pathological glioma grade." (PMID 32201513, 2020). "In gliomas, overexpression of FRAT1 is correlated with a malignant phenotype, higher cell proliferation, decreased apoptosis and poor prognosis." (PMID 28340489, 2017). "FRAT1, thus, acts as a potent oncogene in the induction of Wnt signaling and positively correlates with increasing grade of glioma." (PMID 27043632, 2016).
glioma (continued). "Other means of Wnt pathway deregulation in glioma involve FRAT1 (frequently rearranged in advanced T cell lymphoma) that works to inhibit β-catenin phosphorylation by GSK." (PMID 27043632, 2016). "In the current study, we confirmed that FRAT1 is generally overexpressed in gliomas and that the expression levels of FRAT1 are significantly positively correlated with increasing WHO grades." (PMID 25922553, 2015). "To verify these findings for the cohort of 68 glioma patients in this study, we assessed the FRAT1 immunoreactivity of stained sections." (PMID 25922553, 2015). "In the present study, we investigated the expression status of FRAT1 in 68 patients with human gliomas and its correlation with the pathologic grade, proliferation, invasion, angiogenesis, and prognostic significance." (PMID 25922553, 2015). "Recently, we demonstrated that FRAT1 expression is elevated in gliomas and that its expression is correlated with pathologic grade, proliferation, and apoptosis in astrocytomas." (PMID 25922553, 2015). "Our previous results suggest that FRAT1 is overexpressed in gliomas as assessed by RT-PCR, western blotting, and immunohistochemistry." (PMID 25922553, 2015). "To confirm these results, we divided the 68 glioma specimens into two groups based on FRAT1 positivity." (PMID 25922553, 2015). "In the current study, we confirmed that FRAT1 is overexpressed in three established glioma cell lines." (PMID 23613813, 2013). "We also demonstrated that cytoplasm and/or nucleus accumulation of β-catenin is closely correlated with high FRAT1 expression in human gliomas." (PMID 23613813, 2013). "In the present study, we investigated FRAT1 expression levels in three established glioma cell lines (U87, U251 and SHG44)." (PMID 23613813, 2013). "The results showed that FRAT1 was highly expressed in the three glioma cell lines compared with the normal astrocytes, and that the expression level of FRAT1 was the highest in U251 cells." (PMID 23613813, 2013). "In the current study, we used RT-PCR and Western blotting to assess the mRNA and protein levels of FRAT1 in three glioma cell lines." (PMID 23613813, 2013). "To study the role of FRAT1 in the malignant progression of glioma, we established a stably transfected U251 cell line expressing shRNA against FRAT1." (PMID 23613813, 2013). "We previously demonstrated that FRAT1 was overexpressed in all grades and most subtypes of resected glioma tested." (PMID 23613813, 2013). "Our findings suggest that FRAT1 RNAi can also significantly suppress tumorigenesis and growth of transplanted U251-derived tumors in nude mice, and that this suppression may be associated with remarkable inhibition of proliferation and invasion of human glioma cells." (PMID 23613813, 2013). "Our previous study showed that aberrant expression of FRAT1 is significantly correlated with the pathologic grade and tumor proliferation rate in surgically resected glioma tissues, implying an oncogenic role for FRAT1 in gliomagenesis." (PMID 23613813, 2013). "Our previous studies showed that FRAT1 was dramatically overexpressed in gliomas and its expression level was significantly increased along with clinicopathological grades." (PMID 23613813, 2013). "Also, most previous studies have reported that FRAT1 expression is positively correlated with increasing WHO glioma grade or the expression level of β-catenin." (PMID 38672212, 2024). "Based on our findings, we hypothesized that the effects of FSTL1 and CER1 in grade III gliomas are stronger, whereas those of FRAT1 and BMP2 are weaker." (PMID 38672212, 2024). "Our previous work has clarified the oncogenic role of FRAT1 in glioma." (PMID 32201513, 2020). "FRAT1 downregulation inhibits the proliferation, migration, and invasiveness of glioma cells." (PMID 32201513, 2020).
glioma (continued). "Thus, glioma tissues of tumor-bearing mice with low FRAT1 mRNA and protein expression also had low in β-catenin mRNA and protein expression, suggesting a positive correlation between FRAT1 and β-catenin expression." (PMID 32201513, 2020). "Our work has found that the expression of FRAT1 and β-catenin was reduced in glioma tissues of tumor-bearing mice and there was a positive correlation between FRAT1 and β-catenin protein expression, which suggested that low FRAT1 inhibited the expression of β-catenin." (PMID 32201513, 2020). "We propose that FRAT1 may be a useful biomarker for molecular diagnosis, an indicator for the prognosis of glioma, and an intriguing candidate target for glioma therapy." (PMID 25922553, 2015). "Collectively, these results demonstrate that FRAT1 expression may serve as a biomarker for gliomas of different pathological grades and with different malignancy characteristics." (PMID 25922553, 2015). "Collectively, these observations suggest that FRAT1 may play a pivotal role in the development and progression of gliomas due to its multiple biologic activities involved in promoting proliferation, invasion, and angiogenesis." (PMID 25922553, 2015). "In addition, to evaluate its functional role in gliomas, we examined the effects of FRAT1 knockdown on proliferation, migration and invasion in vitro and tumor growth in vivo using glioblastoma U251 cells and RNAi." (PMID 23613813, 2013). "We propose that, based on both its expression pattern and its demonstrated functional role, FRAT1 may also be useful as a valuable biomarker for the molecular diagnosis of glioma and a promising candidate target for glioma therapy." (PMID 23613813, 2013). "Expression levels of FRAT1 mRNA and protein in several high grade glioma-derived cell lines cultured in vitro, including SHG44, U87, and U251, were compared to expression levels in normal human cultured primary astrocytes (N) by RT-PCR and Western blot analysis." (PMID 23613813, 2013). "In summary, these observations, together with our previous study, suggest that FRAT1 may play a pivotal role in the development and progression of gliomas." (PMID 23613813, 2013). "Furthermore, in retrospective studies, the expression level of FRAT1 was positively correlated with increasing pathologic grade and glioma proliferation, and was negatively correlated with tumor apoptosis." (PMID 23613813, 2013). "Therefore, inhibiting proliferation of GSCs and FRAT1 may be a molecular target to GSCs in treating human glioma in the future." (PMID 32201513, 2020). "However, little is known about the contribution of FRAT1 expression to the prognosis of glioma." (PMID 25922553, 2015). "Thus, the mechanistic function and expression pattern of FRAT1 suggests that it might be involved in tumorigenesis and malignant progression of glioma under certain pathological conditions." (PMID 23613813, 2013). "To verify whether the effect of FRAT1 RNAi on growth of glioma cells is also observed in vivo, we injected parental U251, U251-neo, U251-NC or U251-S cells into nude mice to develop subcutaneous glioma xenografts." (PMID 23613813, 2013). "The apparent correlation of high levels of FRAT1 expression with the more advanced stages of glioma and other cancers is suggestive of its potential as a selective target for therapeutics; however, cell-specific targeting could also potentially be employed to provide additional selectivity." (PMID 23613813, 2013). "Conversely, the expression of genes related to good prognosis, such as FRAT1 and BMP2, was significantly lower in grade III than in grade II gliomas." (PMID 38672212, 2024). "Altogether, results indicate that FRAT1 enhances the proliferation, colony formation, sphere formation and tumorigenesity of CD133+Nestin+ glioma stem cells in vitro and in vivo as well as the expression of β-catenin." (PMID 32201513, 2020).
glioma (continued). "In contrast, if the actions of FRAT1 and BMP2 become stronger and those of FSTL1 and CER1 become weaker in patients with grade III gliomas, the difference in survival and disease progression between these opposing groups may significantly increase." (PMID 38672212, 2024). "We do not know the exact mechanism of why the overexpression of FRAT1, a Wnt/β-catenin signaling-related oncogene, improves the prognosis in patients with glioma." (PMID 38672212, 2024). "However, the expression of FRAT1 in specific glioma cell lines has not been elucidated." (PMID 23613813, 2013). "However, previous studies on glioma and FRAT1 have mostly focused on glioblastoma, a WHO grade IV glioma, rather than the grade II or III gliomas considered in this study." (PMID 38672212, 2024).
ovarian carcinoma (6 papers, 2006 to 2023). A malignant neoplasm originating from the surface ovarian epithelium. "As an extensively recognized oncogene, FRAT1 is overexpressed in ovarian cancer 42, non-small cell lung cancer 43, pancreatic cancer 44, gastric cancer 45, and liver cancer 46, and it is associated with poor clinical prognosis." (PMID 32201513, 2020). "We demonstrate here that FRAT1 is expressed in some human normal tissues and overexpressed in human ovarian cancer." (PMID 16479254, 2006). "In this study, we used in situ hybridisation probes to demonstrate the presence of FRAT1 in paraffin-embedded human normal tissues and ovarian cancer tissues." (PMID 16479254, 2006). "Thus, it is reasonable that FRAT1 has been found to be strikingly overexpressed in several human cancers, including esophageal cancer, cervical cancer, breast cancer, ovarian cancer, and non-small-cell lung cancer." (PMID 25922553, 2015). "However, whereas FRAT1 is a candidate for the regulation of cytoplasmic β-catenin, little is known with regard to the molecular relationship between FRAT1 and β-catenin in ovarian cancer." (PMID 16479254, 2006). "In this study, we developed in situ hybridisation probes to evaluate the presence of FRAT1 and used an anti-β-catenin antibody to evaluate by immunohistochemistry the expression levels and subcellular localisation of β-catenin in ovarian cancer tissue microarrays." (PMID 16479254, 2006). "A study with larger cohort seems mandatory to clarify whether the same role of FRAT1 exists in other histological subtypes of ovarian cancer, such as clear cell, endometrioid and mucinous adenocarcinomas." (PMID 16479254, 2006). "The FRAT1 and FRAT2 genes are clustered in the human chromosome locus 10q24.1, and both genes have been previously identified as proto-oncogenes in a variety of tumours, including basal-like breast cancer, ovarian cancer, and GC." (PMID 36153370, 2022). "Furthermore, instances of FRAT1 overexpression have been documented in various cancers, including ovarian cancer, gastric cancer, esophageal squamous cell carcinoma, and non-small cell lung cancer." (PMID 38136890, 2023). "Thus it is not surprising that FRAT1 has been found to be strikingly overexpressed in several human cancers including esophageal cancer, cervical cancer, breast cancer, ovarian cancer, and non-small cell lung cancer." (PMID 23613813, 2013).
non-small cell lung carcinoma (5 papers, 2013 to 2023). A group of at least three distinct histological types of lung cancer, including non-small cell squamous cell carcinoma, adenocarcinoma, and large cell carcinoma. "Overexpression of Frat1 and abnormal expression of β-catenin were found to represent a poor prognosis for the non-small cell lung cancer patients." (PMID 32212785, 2020).
prostate carcinoma (5 papers, 2020 to 2024). A carcinoma that arises from epithelial cells of the prostate gland. "A prior study demonstrated that the expression levels of FRAT1 were modified through overexpression or RNA interference-induced depletion in prostate cancer cells." (PMID 38136890, 2023). "Frat1 demonstrates oncogenic properties in prostate cancer by inhibiting GSK 3β against β-catenin and thus promoting cell growth, while Frat2 mediates the oncogenic activation of Rac by mixed lineage leukemia fusions." (PMID 32212785, 2020). "Goksel and colleagues 48 revealed that FRAT1 expression is significantly upregulated in CD133+ CD44+ prostate cancer stem cells and FRAT1 overexpression activates Wnt/β-catenin signaling pathway by inducing β-catenin/TCF activity." (PMID 32201513, 2020). "However, similar to our previous investigation examining colon and prostate cancer cells, NDRG1 overexpression in PANC-1 cells significantly increased (p < 0.001) the expression of the GSK-3β-binding protein, frequently rearranged in advanced T-cell lymphoma (FRAT1), relative to VC cells." (PMID 38815861, 2024).
cervical cancer (4 papers, 2013 to 2021). A primary or metastatic malignant neoplasm involving the cervix. "Both public available TCGA data and cervical cancer tissues we collected display that the expression of FRAT1 and FRAT2 are positively associated with the expression of DANCR in cervical cancer tissues, supporting the positive regulation of FRAT1 and FRAT2 by DANCR." (PMID 32123519, 2020). "Pearson correlation analysis displayed that the expression of FRAT1 and FRAT2 were both positively associated with the expression of DANCR in cervical cancer tissues." (PMID 32123519, 2020). "In this study, we identified a novel mechanism mediating the oncogenic roles of DANCR in cervical cancer, which is the activation of the Wnt/β-catenin signalling pathway via upregulation of FRAT1 and FRAT2." (PMID 32123519, 2020). "DANCR promotes cervical cancer growth via activating FRAT1/FRAT2-Wnt/β-catenin signaling pathway." (PMID 32123519, 2020). "Our results displayed that enhanced expression of DANCR upregulated the mRNA and protein expression levels of FRAT1 and FRAT2, and while knockdown of DANCR downregulated the mRNA and protein expression levels of FRAT1 and FRAT2 in cervical cancer cells." (PMID 32123519, 2020).